IL17RA (interleukin 17 receptor A)
Description:
Receptor for IL17A and IL17F, major effector cytokines of innate and adaptive immune system involved in antimicrobial host defense and maintenance of tissue integrity. Receptor for IL17A. Receptor for IL17F. Binds to IL17A with higher affinity than to IL17F. Binds IL17A and IL17F homodimers as part of a heterodimeric complex with IL17RC. Also binds heterodimers formed by IL17A and IL17F as part of a heterodimeric complex with IL17RC. Cytokine binding triggers homotypic interaction of IL17RA and IL17RC chains with TRAF3IP2 adapter, leading to TRAF6-mediated activation of NF-kappa-B and MAPkinase pathways, ultimately resulting in transcriptional activation of cytokines, chemokines, antimicrobial peptides and matrix metalloproteinases, with potential strong immune inflammation. Involved in antimicrobial host defense primarily promoting neutrophil activation and recruitment at infection sites to destroy extracellular bacteria and fungi (By similarity). In secondary lymphoid organs, contributes to germinal center formation by regulating the chemotactic response of B cells to CXCL12 and CXCL13, enhancing retention of B cells within the germinal centers, B cell somatic hypermutation rate and selection toward plasma cells (By similarity). Plays a role in the maintenance of the integrity of epithelial barriers during homeostasis and pathogen infection. Stimulates the production of antimicrobial beta-defensins DEFB1, DEFB103A, and DEFB104A by mucosal epithelial cells, limiting the entry of microbes through the epithelial barriers (By similarity). Involved in antiviral host defense through various mechanisms. Enhances immunity against West Nile virus by promoting T cell cytotoxicity. Contributes to Influenza virus clearance by driving the differentiation of B-1a B cells, providing for production of virus-specific IgM antibodies at first line of host defense (By similarity). Receptor for IL17C as part of a heterodimeric complex with IL17RE. (Microbial infection) Receptor for SARS coronavirus-2/SARS-CoV-2 virus protein ORF8, leading to IL17 pathway activation and an increased secretion of pro-inflammatory factors through activating NF-kappa-B signaling pathway.
Synonyms: IL-17RA; CD217; IL17R; hIL-17R; CDw217; CANDF5; IMD51
Tractability: Antibody: an approved drug acts on it; UniProt places it where antibodies can reach, with high confidence; its Gene Ontology location is reachable by antibodies, with high confidence; UniProt predicts a signal peptide or a membrane-spanning region. PROTAC: ubiquitination databases record sites on it; its protein half-life has been measured.
Target class: Membrane receptor
Gene: Protein-coding gene on chromosome 22 (17,084,934 to 17,115,693, forward strand). Ensembl gene ENSG00000177663.
Subcellular location: Cell membrane (Isoform 1); Secreted (Isoform 2)
Subcellular location (Human Protein Atlas): Cytosol; Nucleoplasm; Predicted to be secreted
Pathways (Reactome):
Disease: SARS-CoV-2 activates/modulates innate and adaptive immune responses
Immune System: Interleukin-17 signaling
Gene Ontology:
Molecular function: interleukin-17 receptor activity; protein binding; signaling receptor binding
Biological process: fibroblast activation; interleukin-17-mediated signaling pathway; interleukin-17A-mediated signaling pathway; positive regulation of chemokine (C-X-C motif) ligand 1 production; positive regulation of cytokine production involved in inflammatory response; positive regulation of inflammatory response; positive regulation of interleukin-23 production; positive regulation of interleukin-6 production; response to virus; cell surface receptor signaling pathway; positive regulation of interleukin-13 production; positive regulation of interleukin-5 production; protein K63-linked ubiquitination; regulation of cell growth; regulation of keratinocyte proliferation; T-helper 17 type immune response; defense response to fungus; granulocyte chemotaxis; protein catabolic process
Cellular component: extracellular region; plasma membrane
Genetic constraint (gnomAD): Loss-of-function variants: 37 observed, 54.26 expected, observed/expected ratio (o/e) 0.68, 90% interval 0.52 to 0.9. The synonymous counts are far from expectation, so gnomAD's model fits this gene poorly and the ratio says little. Missense variants: 1,276 observed, 1,140.3 expected, observed/expected ratio (o/e) 1.12, 90% interval 1.07 to 1.17. Synonymous variants: 585 observed, 490.77 expected, observed/expected ratio (o/e) 1.19, 90% interval 1.11 to 1.28.
Homologues: Orthologues: chimpanzee IL17RA (99% identical), macaque IL17RA (95% identical), rabbit IL17RA (72% identical), dog IL17RA (70% identical), guinea pig IL17RA (69% identical), mouse Il17ra (68% identical), rat Il17ra (68% identical), pig IL17RA (67% identical). Paralogues in human: IL17RD (17% identical), IL17RB (14% identical), IL17RC (11% identical), IL17RE (9% identical).
Diseases named in the same sentence as IL17RA in open-access papers:
IL17RA is named in the same sentence as 263 diseases in open-access papers, as found by Europe PMC text mining. Sharing a sentence is not in itself a finding about the gene and the disease. The quoted sentences say what the papers report.
psoriasis (102 papers, 2010 to 2026). An autoimmune condition characterized by red, well-delineated plaques with silvery scales that are usually on the extensor surfaces and scalp. "Monoclonal antibodies designed to target IL-17A, IL-17F, IL-17RA, and IL-23 have been authorized for clinical use in treating IL-17-associated autoimmune disorders, such as psoriasis." (PMID 40536951, 2026). "We found novel psoriasis susceptibility variants centred on the 5’ untranslated region of IL17RA at chromosome 22q11.1 (lead variant rs917864, OR: 1.08, P = 3.9 × 10−9)." (PMID 40021644, 2025). "By identifying psoriasis as a novel phenotype alongside CMC for being associated with IL17RA variants, our findings expand the current understanding of IL17RA’s diverse roles in health and diseases." (PMID 39911581, 2024). "This study marks an unprecedented advancement in the understanding of these conditions by reporting the first mutation in IL17RA bridging psoriasis and CMC immunogenetic elements." (PMID 39911581, 2024). "On the other hand, the association between IL17RA and psoriasis has been explored through association studies only, identifying a single nucleotide polymorphism (SNP) in IL17RA (rs4819554) that increases psoriasis risk in Spanish and Egyptian populations." (PMID 39911581, 2024). "Novel pathogenic biallelic nonsense variant (NM_014339.6) c.1173C>G identified in the IL17RA gene by Whole Exome Sequencing in a 5-year-old child with psoriasis and chronic mucocutaneous candidiasis, expanding the range of IL17RA variant-associated phenotypes." (PMID 39911581, 2024). "Based on currently available data, IL-17F and IL-17RA gene variants have significant effects on psoriasis." (PMID 37239484, 2023). "Polymorphism rs4819554 of the IL-17RA gene is more frequently associated with nail psoriasis in patients with psoriasis who have the GG genotype compared to those with GA/AA genotype (p = 0.02)." (PMID 37239484, 2023). "The IL17 family has also been reported to play a key role in many IIME remodeling-associated diseases, such as psoriasis, yet the association between IL17RA and IC/BPS remains to be further clarified." (PMID 36979355, 2023). "In different populations, SNPs belonging to IL-17RA or IL-17F and other pro-inflammatory cytokines have been associated with the susceptibility to develop psoriasis or psoriatic arthritis and with the response to biological treatment." (PMID 37239484, 2023). "They found that only IL-17RA deletion in keratinocytes significantly protected mice from IMQ-induced psoriasis-like dermatitis, which is similar to full-body deficiency of IL-17RA." (PMID 35075118, 2022). "Interleukin-17 receptor A (IL-17RA) is a valuable biomarker associated with numerous autoimmune diseases including psoriasis, inflammatory bowel disease, asthma, type 1 diabetes, rheumatoid arthritis, and MS." (PMID 36015143, 2022). "Genetic variability in the area of IL12B and IL17RA has previously been associated with psoriasis in many studies." (PMID 31211819, 2019). "IL17RA plays a pathogenic role in many inflammatory and autoimmune diseases, including rheumatoid arthritis, psoriasis, Candida albicans infection and Crohn disease." (PMID 29554915, 2018). "No variants in the IL-17A gene itself was shown to predispose to psoriasis so far, whereas the IL-17RA allele rs4819554 was recently associated with risk of developing psoriasis in a Spanish cohort." (PMID 30127781, 2018). "We then took advantage of the IMQ-induced psoriasis–like model and determined whether the loss of IL-17A signaling in IL-17RA–deficient mice (IL17ra–/–) would affect AIM2 expression in the skin." (PMID 39352743, 2024). "Although monoclonal antibodies that specifically target IL23, IL17, and IL17 receptor A (IL17RA) significantly improve psoriasis symptoms, the therapy cannot eliminate pathogenic T cells, which subsequently contribute to a relapse of psoriasis through again provoking keratinocytes." (PMID 36009523, 2022).
psoriasis (continued). "IL-17RA rs48419554 was also identified as a risk factor for psoriasis." (PMID 34744511, 2021). "A loss-of-function mutation of the IL17RA transmembrane protein could be identified as most likely pathogenic variant for the psoriasis-like skin alterations observed in the two affected Holstein calves." (PMID 32448141, 2020). "The reported loss of function IL17RA mutation in cattle might suggest a phenotype like psoriasis." (PMID 39911581, 2024). "Further support for this link comes from the findings that neutralizing antibodies directed against IL-17A, IL-17RA and IL-23 are efficacious in diseases like psoriasis, psoriatic arthritis and ankylosing spondylitis." (PMID 39820614, 2025). "Secukinumab, ixekizumab, and bimekizumab are monoclonal antibodies targeting IL17A/IL17RA, which are approved in clinical use to treat psoriasis." (PMID 39959414, 2025). "Eventually, IL17RA L-SNAs were suggested as a promising topical delivery platform for IL17RA targeted therapy for psoriasis." (PMID 38951806, 2024). "Previous studies have shown the upregulation of IL17RA in keratinocytes and immune cells during the development of psoriasis." (PMID 38951806, 2024). "Since 2015, biologics targeting IL‐17A, IL‐17F, IL‐17RA, and IL‐23p19 have become available in Japan, thus expanding treatment options for patients with psoriasis." (PMID 39269210, 2024). "Another psoriasis pathogenesis mechanism is Th17 signaling, which is initiated with IL-17 A binding to its receptor (IL17RA)." (PMID 38951806, 2024). "We next analyzed a public GEO database (GSE117468) to assess the relative expression of AIM2 mRNA in lesioned skin biopsies from patients with psoriasis who were treated with brodalumab, a human monoclonal antibody targeting the receptor subunit IL-17RA." (PMID 39352743, 2024). "TNF and IL17RA have been shown to have synergistic effects in psoriasis, and both are approved by the U.S. Food and Drug Administration as pharmacotherapeutic targets in psoriasis." (PMID 36979355, 2023). "Brodalumab (AMG827; KHK4827) is a fully human IgG2 mAb that works by blocking the IL-17RA chain of the IL-17 receptor on the cell surface compared to the first two antibodies, and is the first anti-IL-17RA inhibitor to treat psoriasis." (PMID 37859999, 2023). "Brodalumab, a human monoclonal antibody against IL-17RA, which mediates the downstream signaling of IL-17A, IL-17F, IL-17A/F, IL-17C, and IL-17E, has been approved for the treatment of psoriasis." (PMID 35626662, 2022). "Our data demonstrated that Il17ra(T779A)-KI and Il17rc-KO prevent the development of psoriasis and tumorigenesis in the skin, while the topical administration of centrinone does not have any effect." (PMID 36009523, 2022). "Our study has confirmed the important role of the IL17RA/IL17RC heterodimer in promoting keratinocyte proliferation in psoriasis and skin papilloma models." (PMID 36009523, 2022). "Il17ra(T779A)-KI significantly inhibited skin papilloma formation, but only slightly decreased epidermal thickening in the psoriasis model." (PMID 36009523, 2022). "The proliferative signaling of keratinocytes is initiated by IL17 through recruitment of IL-17RA/IL-17RC and then Act1, which is assumed to explain the link between psoriasis and skin tumorigenesis." (PMID 36009523, 2022). "To test this prediction, we generated the Il17ra(T779A)-KI mouse strain and used imiquimod to induce psoriasis." (PMID 36009523, 2022). "In contrast, deficiency of Il17rc completely abolished the thickening of the epidermis and the proliferation of keratinocytes, which verified the key role of IL17RA/IL17RC complex in the development of psoriasis." (PMID 36009523, 2022). "An imiquimod-induced psoriasis model was established in WT, Il17ra(T779A)-KI, and Il17rc-KO mouse strains." (PMID 36009523, 2022). "Monoclonal antibodies against IL17 and IL17RA have been approved for the treatment of psoriasis in clinical practice." (PMID 36009523, 2022).
psoriasis (continued). "In clinical trials, the antibodies of IL-23p19, IL-23p40, IL-17A, and IL-17RA have shown promising efficacy in the treatment of many autoimmune diseases including psoriasis, ankylosing spondylitis, and multiple sclerosis." (PMID 35528611, 2022). "In psoriasis, IL-17A directly enhances keratinocyte gene expression, such as that of cathelicidin (LL-37) antimicrobial peptides, via its target receptors, IL-17RA and IL-17RC." (PMID 35203707, 2022). "In the psoriasis model, compared to WT and Il17ra(T779A)-KI, Il17rc-KO dramatically suppressed epidermal thickening." (PMID 36009523, 2022). "We found that transcription levels of IL17A, IL17C, and IL17F were increased in psoriasis compared with normal skin, which was in parallel with their receptors IL17RA, IL17RC, IL17RD, and IL17RE." (PMID 36009523, 2022). "This article reviews current evidence on the biology and role of the IL-17 family of cytokines and receptors, with focus on IL-17RA, in psoriasis and some related comorbidities, and puts them in context with current and upcoming treatments." (PMID 34201664, 2021). "IL-17A seems to fulfil a key role in the pathway of the pathogenesis of psoriasis, and biological therapies targeting IL-17A and/or IL-17RA yield remarkable effects for inflammatory skin dermatoses like psoriasis." (PMID 34945130, 2021). "Biologic agents targeting IL-17A or IL-17RA have been demonstrated to have considerable clinical impact in the treatment of psoriasis, and this further proves the vital role of IL-17A in psoriasis." (PMID 35186952, 2021). "The present study examines the expression of the genes IL-10, IL-17A, IL-17RA, IL-23A and IL-23R in the skin and peripheral blood of patients with psoriasis and of healthy people, to identify potential factors regulating the development of psoriatic lesions." (PMID 34945130, 2021). "Biologics targeting IL-17A alone or in combination with IL-17F or the IL-17 receptor A (IL-17RA) are efficacious in the treatment of plaque psoriasis, highlighting the central role of the IL-17A pathway in psoriasis pathogenesis." (PMID 34616394, 2021). "IL-10, IL-17A, IL-17RA (interleukin 17A receptor), IL-23A (interleukin 23 subunit α) and IL-23R (interleukin 23 receptor) in the development of psoriasis." (PMID 34945130, 2021). "The expression of the IL-17 receptor, IL-17RA and IL-17RC, was confirmed on skin fibroblasts from psoriasis patients or healthy volunteers." (PMID 34616394, 2021). "Brodalumab is a human mAb that binds with high affinity to human IL-17 receptor A (IL-17RA) and can lead to a significantly efficacious therapeutic alternative for psoriasis and psoriatic arthritis." (PMID 32398096, 2020). "Antibodies against IL-17A or IL-17RA are proven to be effective in the treatment of psoriasis in humans." (PMID 31936879, 2020). "The involvement of IL-17 and its receptor IL17RA has been shown in respect to psoriasis and psoriatic arthritis in humans and mice." (PMID 32448141, 2020). "Other antibodies directly targeting IL-17A (Secukinumab, Ixekizumab) or the receptor IL-17RA (Brodalumab) show astonishing effects in psoriasis patients." (PMID 32174926, 2020). "First antibodies that target IL-17A or its receptor IL-17RA are approved for the treatment of psoriasis." (PMID 32010143, 2019). "Neutralization of IL-17A (secukinumab and ixekizumab) or the receptor subunit IL17RA (brodalumab) via monoclonal antibodies represents a highly effective approach to treat psoriasis." (PMID 30127781, 2018). "Antibodies targeting IL-17A or its receptor IL-17RA show unprecedented efficacy in the treatment of autoimmune diseases such as psoriasis." (PMID 27853279, 2016). "Keratinocytes are the predominant cells that express IL-17 receptors (IL-17R; likely consisting of two IL-17RA subunits complexed with one IL-17RC subunit) in psoriasis." (PMID 26573299, 2016). "Of note, an antibody blocking the IL-17 receptor A (IL-17RA) is also effective in psoriasis and is in phase 3 development." (PMID 27158469, 2016).